CDK4 (cyclin dependent kinase 4)
Diseases named in the same sentence as CDK4 in open-access papers (continued):
Sharing a sentence is not in itself a finding about the gene and the disease.
non-small cell lung carcinoma (continued). "A previous study found that downregulation of RCC1 could sensitize immunotherapy by upregulating PD-L1 via the p27kip1/CDK4 pathway in non-small cell lung cancer, and the expression of RCC1 was inversely related to the amount of immune cell infiltration." (PMID 34924821, 2021). "We previously reported that SFN-Cys might activate 26S proteasome in human non-small cell lung cancer cells, thus CDK4/CDK6 might be degraded by the ubiquitin-proteasome pathway." (PMID 32860670, 2020). "Combination treatment of an EGFR sensitive non-small cell lung cancer PDX model with a CDK4/6 inhibitor and an EGFR inhibitor showed combinatorial benefit, providing precedent for a similar application in chordoma tumors which are also sensitive to EGFR inhibition." (PMID 32737414, 2020). "For example, CDK4 gene knockout could immediately induce the senescence of non-small cell lung cancer cells driven by K-Ras, thus resulting in tumor regression." (PMID 33330071, 2020). "CDK4 is emerging as a target in KRAS-mutant non-small cell lung cancer (NSCLC)." (PMID 30167080, 2018). "Co-targeting of MEK and AKT signaling showed some durable response in a phase I study, and most recently, a small trial showed some success combining an investigational MEK inhibitor with a CDK4/6 inhibitor in non-small cell lung cancer (NSCLC) (trial NCT number NCT02022982)." (PMID 30053901, 2018). "Furthermore, abrogation of CDK4 was synthetically lethal in KRAS mutant non-small cell lung cancer models." (PMID 27167191, 2016). "Besides, puromycin proved to promote the function of farnesiferol c in downregulating CCND1 and CDK4 in non-small-cell lung cancer cells, which not only supports the scientific hypothesis but also provides a new clue for LGG treatments." (PMID 36703644, 2023). "For instance, CDK4/6 inhibitors can sensitise BRG1-defective cancer cells, especially in small cell carcinoma of the ovary hypercalcemic type (SCCOHT) and Non-small cell lung cancer (NSCLC) due to the downregulation of cyclin D1." (PMID 41278204, 2025). "In certain patients with immunotherapy-tolerant advanced non-small-cell lung cancer (NSCLC), the combination of CDK4/6 inhibitors and anti-PD-1 agents has shown unexpected clinical benefits." (PMID 39593745, 2024). "In non-small cell lung cancer (NSCLC), YTHDF1 was reported to promote cancer cell proliferation and tumor progression by regulating the translational efficiency of CDK2, CDK4, and cyclin D192." (PMID 33795663, 2021). "The genes included the pathway non-small cell lung cancer were E2F2, E2F3, TGFA, PRKCG, CDK6, EGF, and CDK4, which were all expressed at significantly higher levels in LUSC tissues in comparison to that in the non-cancer group." (PMID 29394946, 2018). "Inhibition of CDK4 was found to be synthetically lethal in vitro and in vivo in KRAS mutant non-small cell lung cancers." (PMID 27167191, 2016). "In non-small cell lung cancer (NSCLC), piR-651 upregulation correlates with a significant increase in tumor growth and metastasis, affecting cell cycle arrest and inducing cyclin D1 and CDK4 and suggesting piR-651 as a potential oncogene." (PMID 37568728, 2023). "Furthermore, we found that YTHDF1 expression is decreased in highland mammals compared to lowlanders, which promotes non-small cell lung cancer (NSCLC) progression by activating the translational efficiency of m6A modified CDK2 and CDK4 mRNAs." (PMID 34805153, 2021). "In addition, YTHDF1 promoted non-small cell lung cancer cell proliferation through regulating the translational efficiency of CDK2, CDK4, and cyclin D1." (PMID 33726814, 2021). "Furthermore, up-regulated piR-651 in non-small cell lung carcinoma (NSCLC) may induce oncogene expression, such as cyclin D1 and cyclin-dependent kinase 4 (CDK4), although the exact mechanism remains unclear." (PMID 31399034, 2019).
non-small cell lung carcinoma (continued). "Besides, marmesin inhibits pRb phosphorylation in human umbilical vein endothelial cells (HUVECs) and in non-small cell lung cancer (NSCLC) cell lines (A549 and H1299) by suppressing the expression of Cdk4 and cyclin D; hence, the cell cycle is halted." (PMID 30347850, 2018). "In addition, various other cancers, including pancreatic ductal adenocarcinoma, non-small cell lung cancer (NSCLC), and melanoma, frequently show cyclin D1 overexpression and amplification, which emphasizes the potential use of CDK4/6 inhibitors in their treatment." (PMID 36675501, 2023). "When non-small cell lung cancer (NSCLC) cells were in a normoxia state, overexpression of YTHDF1 promoted tumor cells proliferation and xenograft tumor formation by augmenting the translations of m6A-marked CDK2, CDK4, and cyclinD1, three key regulators in the G0/G1 cell cycle transition." (PMID 32276589, 2020). "Similarly, radiosensitivity and apoptosis were induced by miR-22-mediated inhibition of SIRT1 in breast cancer cells, by miR-34a-mediated inhibition of LyGDI in non-small cell lung cancer (NSCLC) cells and by miR-124-mediated inhibition of CDK4 in ESCC and glioma cells." (PMID 32585857, 2020).
gastric cancer (73 papers, 1999 to 2026). A primary or metastatic malignant neoplasm involving the stomach. "We found that the increased PGRN was positively associated with CDK4 expression in gastric cancer tissue." (PMID 35880418, 2022). "By analyzing the correlation between PGRN and CDK4, we found that PGRN was positively associated with CDK4 in gastric cancer, and the correlation coefficient r was 0.452." (PMID 35880418, 2022). "For example, CDK4/6-inhibitor resistance in human gastric cancer was shown to be associated with the second arm of the cell cycle/RB/E2F pathway – Cyclin E and CDK2." (PMID 30890123, 2019). "Activation of YAP/TEAD transcription through transcriptional down-regulation of the hippo regulator LATS2 by transcription factor PAX6 led to CDK4/6 inhibitor resistance in gastric cancer cells." (PMID 40699853, 2025). "Neferine inhibits the proliferation of gastric cancer cells by suppressing the expression of the cycling complex CDK4/CDK6/CyclinD1." (PMID 40138292, 2025). "The elevated expression of PGRN can subsequently modulate G2/M stage and CDK4 to promote cell cycle progression, leading to the proliferation and migration of gastric cancer cells." (PMID 39145305, 2024). "Considering the impact of LETM2 on cell cycle progression in gastric cancer, we conducted Western Blot experiments to evaluate the expression of G0/G1 phase-associated cyclins, CDK2, CDK4, CDK6, CyclinB1, and CyclinE2." (PMID 38654380, 2024). "The orphan nuclear receptor (Nurr1) is induced in H. pylori infections via PI3K/AKT-Sp1 mediated fashion and in gastric cancer progression, Nurr1 directly binds with CDK4 promoter site for promoting its transcription and facilitating proliferation." (PMID 36769170, 2023). "Our results provide important preclinical supports for combination therapies with CDK4/6 inhibitors for patients with gastric cancer." (PMID 36755269, 2023). "Dihydroartemisinin (DHA) exerts its anti-tumor activities through inhibition of CDK4 activity and targets Cyclin D1 negatively for induction of cell cycle arrest under in vivo and in vitro conditions in gastric cancer." (PMID 36769170, 2023). "Altogether, these results suggested that CDK4/6 inhibitors induce chromatin remodeling in gastric cancer cells characterized by the extensive enhancer activation and proposed that BRD4 was a promising combination target for ABE." (PMID 36755269, 2023). "The silencing of PAK1 sensitizes cells to CDK4/6 inhibitor in gastric cancer cells in a PDK1-AKT1-dependent pathway." (PMID 36769170, 2023). "The CDK4/6 inhibitor PD-0332991 promotes the apoptosis and senescence of gastric cancer cells and inhibits the migration and invasion of gastric cancer cells." (PMID 36950520, 2023). "KLF5 overexpression enhances the malignancy of gastric cancer via modulating cell cycle proteins p21 and CDK4." (PMID 37181807, 2023). "Immunohistochemical analysis demonstrated that the expression of PGRN and CDK4 in gastric cancer tissue was higher than that in adjacent normal tissue, and PGRN was positively associated with CDK4 in gastric cancer." (PMID 35880418, 2022). "The expression levels of PGRN and CDK4 in adjacent normal tissue and gastric cancer were assessed by immunohistochemical staining." (PMID 35880418, 2022). "We found that in gastric cancer cells CDK4, CDK6 and cyclinD1 were increased upon linc01133 overexpression." (PMID 35017464, 2022). "In this research, we found not only that PGRN and CDK4 were both overexpressed in gastric cancer, but there was also a positive correlation between them." (PMID 35880418, 2022). "Compared with adjacent normal tissue, PGRN and CDK4 expressed significantly higher in gastric cancer tissue." (PMID 35880418, 2022). "In this study, FAT4 repression increased cyclin D1, and cdk4 expression, promoting progression into the G1/S phase of the cell cycle, consistent with results obtained in a previous study on gastric cancer cells." (PMID 32366234, 2020).
gastric cancer (continued). "Simultaneously, changes in the expression of CDK4 and cyclinD1 were detected after HP-CagA+ infection of gastric cancer cells." (PMID 31905669, 2019). "Meanwhile, in HP-CagA+-infected gastric cancer cells, the expression of CDK4 and cyclin D1 was detected when reg3 expression was altered." (PMID 31905669, 2019). "Changes in cell cycle-dependent genes CDK4 and cyclinD1 were detected after upregulation of reg3 in gastric cancer cells." (PMID 31905669, 2019). "DNMT3A also down regulates p18INK4C (an important cell cycle regulator and inhibitor of CDK4/6-CyclinD complexes) in a methylation-dependent manner, which leads to increased cell proliferation in gastric cancer." (PMID 30376837, 2018). "In the present investigation, miR-1 was shown to simultaneously inhibit tumor growth and metastasis of breast and gastric cancers by synchronously targeting CDK4 and TMSB4X, CNN3, TWF1, CORO1C and WASF2 genes." (PMID 28159933, 2017). "Our results suggest that RASSF1A inhibits the proliferation of gastric cancer cells by upregulating the expression of miR-711, which arrested gastric cancer cells in the G1 phase by downregulating expression of CDK4." (PMID 26735582, 2016). "The present study demonstrated that TGF-β1 exerts an antitumor effect on gastric cancer cells through two pathways, cdk4 and p27, by downregulating cdk4 and by upregulating p27." (PMID 23420090, 2013). "In conclusion, certain concentrations of TGF-β1 play antitumor roles in gastric cancer through the downregulation of cdk4 and the upregulation of p27." (PMID 23420090, 2013). "Certain concentrations of TGF-β1 play antitumor roles in gastric cancer through the down-regulation of cdk4 and upregulation of p27." (PMID 23420090, 2013). "While cyclin D1 and CDK4 are well known biomarker of cell proliferation, uPAR and PPARδ have been reported to play role in the migration and invasion of gastric cancer cells." (PMID 22710759, 2012). "Some studies have found that targeting CDK4/CDK6 can treat gastric cancer, and the main mechanism by which this approach exerts its effects is by impeding the cell cycle’s progression from the G1 phase to the S phase, thereby curbing the expansion and proliferation of malignant cells." (PMID 39879230, 2025). "The combination of FAK inhibitors with MAPK inhibitors or CDK4/6 inhibitors may be applied in the development of gastric cancer therapies." (PMID 40104507, 2025). "A long non-coding RNA GCRL1 promotes the metastasis and proliferation of gastric cancer cells under in vitro and in vivo conditions, where it sponges miR-885-3p to positively regulate the CDK4 levels and its invasion and proliferation-related properties and can be targeted for therapy." (PMID 36769170, 2023). "miR-771 inhibits gastric cancer cell proliferation by downregulating CDK4 expression." (PMID 37353691, 2023). "PAX6 activity induces resistance in gastric cancer cells towards Palbociclib targeting CDK4/6." (PMID 36769170, 2023). "In addition, studies has shown that genes such as RN181, KLF16 and PCAF were involved in the progress of gastric cancer by regulating CDK4 levels." (PMID 35494047, 2022). "Whether anti-CDK4/6 therapy provides clinical benefits to gastric cancer patients remains to be determined." (PMID 36612265, 2022). "It is worth performing clinical trials to assess whether P16 methylation could be used to predict the therapeutic efficacy of CDK4/6 inhibitors such as palbociclib in patients with lung and stomach cancers." (PMID 31652270, 2019). "Interestingly, ZNRD1 was found to suppress CDK4, Cyclin D1, and p21 and inhibit the growth of gastric cancer and leukemia cells in vitro." (PMID 28052024, 2017).
gastric cancer (continued). "Thus, it is reasonable that GL-1196 suppressed the PAK4/c-Src/EGFR/cyclinD1 pathway and CDK4/6 expression, which, in turn, inhibited the transition of cells from G1 to S phase, and finally resulted in the anti-proliferative effect on gastric cancer cells." (PMID 27077843, 2016). "These two results confirmed our hypothesis that TGF-β1 exerts an antitumor effect on gastric cancer cell lines through the downregulation of cdks (cdk4) and the upregulation of p27." (PMID 23420090, 2013). "Delayed down-regulation of Cdc25A and cdk4 may contribute to cell adaptation to the quiescent state in the two gastric carcinoma cell lines studied." (PMID 10376964, 1999). "Therefore, we hypothesized that neferine could inhibit gastric cancer proliferation by suppressing the expression of the CDK4/CDK6/CyclinD1 complex." (PMID 40138292, 2025). "The mechanism suggested to be the basis of this differential CK4/6 inhibitor sensitivity of gastric cancer sub-types, p16 methylation, may serve as a biomarker to guide inclusion to a trial of CDK4/6 inhibitor as treatment in gastric cancers or other gastrointestinal trials." (PMID 40699853, 2025). "Dihydroartemisin downregulated PCNA and MMP-2, mediated by p16-Cyclin D1/CDK4-Rb pathway, suppresses the cell growth and metastasis of human gastric cancer (GC) cells." (PMID 39161904, 2024). "Our findings demonstrated that CDKN2A VAR promoted cell proliferation by reducing expression of p16 with function as a regulator of the cell cycle of inhibiting CDK4 and CDK6 in gastric cancer." (PMID 38822443, 2024). "For example, enhanced expression of miR-29a can inhibit mucin 1 (MUC1), reducing the expression levels of cell cycle-dependent kinases CDK2, CDK4, and CDK6, leading to reduced proliferation of gastric cancer cells." (PMID 39519347, 2024). "A long non-coding RNA, GHET1, is upregulated in gastric cancer, and its inhibition in gastric cancer cells leads to reductions in CDK2, Cyclin E1, CDK6, CDK4, and Cyclin D1." (PMID 36769170, 2023). "Pan-cancer analysis revealed that both CDK4 and BRD4 are super essential genes (Gene Effect score < -1) for gastric cancer cells." (PMID 36755269, 2023). "In another study, involving gastric cancer cell line SGC-7901, curcumin treatment led to the stabilization of miR-34a, which in turn inhibited Cyclin D1 and CDK4 from inducing cell cycle arrest and apoptosis." (PMID 36769170, 2023). "Subsequently, both EGR1 and HNF1A-AS1 inhibit p21 via activation of CDK2 and CDK4, adding another layer of regulatory mechanisms involved in the function of CDK2 in the development of gastric cancer." (PMID 36769170, 2023). "CDK4/6 altered frequently in gastric cancer and CDK4/6 inhibitor ABE showed pharmacological efficacy in numerous preclinical models of gastric cancer." (PMID 36755269, 2023). "In summary, we first demonstrated that NOL6 can regulate the oncogenic behaviors of gastric cancer cells by down-regulating TP53I3 and up-regulating CDK4, MCM7." (PMID 35494047, 2022). "To further understand the molecular mechanisms of PGRN regulating cell cycle progression, we turned our attention to CDK4, which is positively correlated with PGRN expression in gastric cancer." (PMID 35880418, 2022). "Furthermore, the predictive markers of CDK4/6 inhibitors in gastric cancer (GC) remain incompletely described." (PMID 34459131, 2021). "Morusin markedly inhibited gastric cancer cell proliferation by down-regulating CDKs and Cyclins, such as CDK2, CDK4, Cyclin D1 and Cyclin E1." (PMID 28915664, 2017). "We found that DIM significantly inhibits gastric cancer cell growth in a dose-dependent manner with G1-phase cell cycle arrest by reducing the levels of the cyclin dependent kinase (CDK) 2, CDK4, CDK6, and Cyclin D1 proteins." (PMID 27447608, 2016).